ALKBH4 (alkB homolog 4, lysine demethylase)
Description:
Dioxygenase that mediates demethylation of actin monomethylated at 'Lys-84' (K84me1), thereby acting as a regulator of actomyosin-processes. Demethylation of actin K84me1 is required for maintaining actomyosin dynamics supporting normal cleavage furrow ingression during cytokinesis and cell migration. In addition to proteins, also demethylates DNA: specifically demethylates DNA methylated on the 6th position of adenine (N(6)-methyladenosine) DNA, thereby regulating Polycomb silencing (By similarity).
Synonyms: ABH4; FLJ20013
Tractability: PROTAC: ubiquitination databases record sites on it; its protein half-life has been measured.
Gene: Protein-coding gene on chromosome 7 (102,456,238 to 102,464,865, reverse strand). Ensembl gene ENSG00000160993.
Subcellular location: Cytoplasm; Nucleus; Nucleus, nucleolus; Midbody
Gene Ontology:
Molecular function: 2-oxoglutarate-dependent dioxygenase activity; actin binding; protein binding; broad specificity oxidative DNA demethylase activity; demethylase activity; DNA N6-methyladenine demethylase activity; protein demethylase activity
Biological process: actomyosin structure organization; cleavage furrow ingression; positive regulation of gene expression, epigenetic; demethylation
Cellular component: contractile ring; cytoplasm; midbody; nucleus; nucleolus
Genetic constraint (gnomAD): Loss-of-function variants: 11 observed, 17.59 expected, observed/expected ratio (o/e) 0.63, 90% interval 0.39 to 1.03. The upper end of that interval is the gene's LOEUF score, 1.03, which puts it in group 4 of 6, group 1 being the genes least tolerant of losing a copy. Missense variants: 403 observed, 409.13 expected, observed/expected ratio (o/e) 0.99, 90% interval 0.91 to 1.07. Synonymous variants: 195 observed, 179.59 expected, observed/expected ratio (o/e) 1.09, 90% interval 0.96 to 1.22.
Homologues: Orthologues: chimpanzee ALKBH4 (99% identical), macaque ALKBH4 (98% identical), dog ALKBH4 (88% identical), pig ALKBH4 (87% identical), mouse Alkbh4 (79% identical), rat Alkbh4 (77% identical), guinea pig ALKBH4 (58% identical), zebrafish alkbh4 (51% identical), Drosophila melanogaster CG4036 (35% identical), Caenorhabditis elegans nmad-1 (31% identical).